GOLIM4 (golgi integral membrane protein 4)
Description:
Plays a role in endosome to Golgi protein trafficking; mediates protein transport along the late endosome-bypass pathway from the early endosome to the Golgi.
Synonyms: GIMPc; GOLPH4; GPP130; P138
Tractability: Antibody: UniProt places it where antibodies can reach, with medium confidence; UniProt predicts a signal peptide or a membrane-spanning region. PROTAC: ubiquitination databases record sites on it; its protein half-life has been measured.
Gene: Protein-coding gene on chromosome 3 (168,008,672 to 168,096,536, reverse strand). Ensembl gene ENSG00000173905.
Subcellular location: Golgi apparatus, Golgi stack membrane; Endosome membrane; Membrane
Subcellular location (Human Protein Atlas): Golgi apparatus
Pathways (Reactome):
Vesicle-mediated transport: Intra-Golgi traffic
Gene Ontology:
Cellular component: Golgi apparatus; membrane; cis-Golgi network; endocytic vesicle; Golgi lumen; Golgi membrane; transport vesicle; endosome membrane; Golgi cisterna membrane
Genetic constraint (gnomAD): Loss-of-function variants: 38 observed, 64.56 expected, observed/expected ratio (o/e) 0.59, 90% interval 0.45 to 0.77. The upper end of that interval is the gene's LOEUF score, 0.77, which puts it in group 3 of 6, group 1 being the genes least tolerant of losing a copy. Missense variants: 522 observed, 558.59 expected, observed/expected ratio (o/e) 0.93, 90% interval 0.87 to 1. Synonymous variants: 213 observed, 208.67 expected, observed/expected ratio (o/e) 1.02, 90% interval 0.91 to 1.14.
Homologues: Orthologues: chimpanzee GOLIM4 (99% identical), macaque GOLIM4 (98% identical), rabbit GOLIM4 (85% identical), pig GOLIM4 (85% identical), dog GOLIM4 (84% identical), mouse Golim4 (82% identical), guinea pig GOLIM4 (82% identical), rat Golim4 (81% identical), tropical clawed frog golim4 (59% identical), zebrafish zgc:66479 (11% identical).
Diseases named in the same sentence as GOLIM4 in open-access papers:
GOLIM4 is named in the same sentence as 15 diseases in open-access papers, as found by Europe PMC text mining. Sharing a sentence is not in itself a finding about the gene and the disease. The quoted sentences say what the papers report.
breast carcinoma (3 papers, 2021 to 2025). "Recently, it was also shown that miR-105-3p acts as an oncogene to promote the proliferation and metastasis of breast cancer cells by silencing GOLIM4 and that targeting miR-942-5p/GPP130 axis suppressed breast cancer malignant behavior." (PMID 40649939, 2025). "Correlation regression analysis showed a negative correlation between the expression levels of miR-105-3p and GOLIM4 in breast cancer tissues (R = -0.39, P = 0.13)." (PMID 33722196, 2021). "MiR-105-3p acts as an oncogene to promote the proliferation and metastasis of breast cancer cells by targeting GOLIM4, which provides a new target for the prevention and treatment of breast cancer." (PMID 33722196, 2021). "Most importantly, silencing GOLIM4 reversed the inhibitory effect on the biological characteristics of breast cancer cells induced by miR-105-3p knockdown in these cancer cells." (PMID 33722196, 2021). "Since GOLIM4 has been identified as a tumour suppressor gene in other kinds of cancers, we confirmed that the elevated expression of miR-105-3p could suppress the expression of GOLIM4 by binding to its 3’UTR in the carcinogenesis of breast cancer." (PMID 33722196, 2021). "In addition, the expression levels of GOLIM4 in breast cancer tissues and cell lines were significantly decreased." (PMID 33722196, 2021). "In addition, silencing GOLIM4 restored the anti-breast cancer effects induced by miR-105-3p downregulation." (PMID 33722196, 2021). "To confirm that miR-105-3p could act as an oncogene to promote the proliferation and metastasis of breast cancer cells by silencing GOLIM4, we silenced the expression of GOLIM4 in the MCF-7 and ZR-75-30 cells transfected with the miR-105-3p inhibitor with sh-GOLIM4." (PMID 33722196, 2021). "Furthermore, miR-105-3p could directly bind to the 3’UTR of GOLIM4 and thus act as a tumour promoter in breast cancer." (PMID 33722196, 2021). "However, the results of the correlation regression analysis showed that the negative correlation (R = -0.39) between the expression levels of miR-105-3p and GOLIM4 in breast cancer tissues was not significant (P = 0.13)." (PMID 33722196, 2021).
head and neck cancer (3 papers, 2021 to 2025). A primary or metastatic malignant neoplasm affecting the head and neck. "Given that dysfunction of the Golgi and endosomes was involved in the progression of various tumours, GOLIM4 was considered to be a tumour suppressor gene in the carcinogenesis of human head and neck cancer." (PMID 33722196, 2021). "Nevertheless, the Golgi apparatus and endosome dysfunction are involved in the progression of various tumors, and increased expression of GOLIM4 has been shown to inhibit cancer cell proliferation, promote apoptosis, and induce G1 phase arrest in human head and neck cancer cell lines." (PMID 37760246, 2023). "The increased expression of GOLIM4 could inhibit the proliferation of neck cancer, promote cell apoptosis and induce G1 phase arrest in human head and neck cancer cell lines, such as FaDu and Tca-8113." (PMID 33722196, 2021). "Hence, we first interrogated a genomics database (cBioPortal for Cancer Genomics) and noted that the GOLIM4/GPP130 gene is amplified in up to ~35% of lung cancer patients, ~20% of ovarian cancer patients, ~15% of cervical cancer and in >10% of head-and-neck cancer patients." (PMID 40649939, 2025). "As shown for head and neck cancer, it is plausible that the knockdown of GPP130 also leads to the perturbation of Stromal Interaction Molecule 1 (STIM1)-GOLIM4 signal axis in A549 cells, thereby reducing the cellular growth." (PMID 40649939, 2025).
lung carcinoma (3 papers, 2024 to 2025). "RNA-Seq studies on GOLIM4-deficient and -replete lung cancer cells showed that GOLIM4-replete cells were relatively enriched in Gene Ontology terms related to secretory processes, including “vesicle cargo loading,” “RAB protein signal transduction,” “monocyte chemotaxis,” and “neuron axon guidance”." (PMID 38662435, 2024). "Arguing against this possibility, GOLIM4 depletion reduced the proapoptotic and antitumor effects of Mn treatment on 3q-amplified lung cancer cells." (PMID 38662435, 2024). "Located on the 3q amplicon, ATP2C1 is coamplified with GOLIM4, and ATP2C1 mRNA levels are correlated with ATP2C1 gene copy numbers and GOLIM4 mRNA levels in TCGA lung cancer cohorts." (PMID 38662435, 2024). "In human lung cancer cell lines that were 3q amplified or 3q diploid, GOLIM4 depletion reduced proliferative, migratory, and colony forming activities to a greater extent in 3q-amplified than in 3q-diploid cells." (PMID 38662435, 2024). "In TCGA lung cancer cohorts, GOLIM4 mRNA levels were positively correlated with gene copy numbers, were higher in malignant lung tissues than in normal lung tissues, and were higher in metastatic deposits than in primary tumors." (PMID 38662435, 2024). "Given that multiple Mn-binding proteins were identified in 3q-amplified lung cancer cells, we asked whether Mn exerts antitumor activity through GOLIM4-independent mechanisms." (PMID 38662435, 2024). "Moreover, ATP2C1 depletion phenocopied the effect of GOLIM4 depletion in 3q-amplified lung cancer cells." (PMID 38662435, 2024). "To test the hypothesis that GOLIM4 is a protumorigenic effector of the 3q amplicon, we first quantified GOLIM4 levels in human lung cancer cell lines classified as 3q amplified or 3q diploid and found that GOLIM4 mRNA and protein levels were higher in 3q-amplified cells." (PMID 38662435, 2024). "ATP2C1 depletion abrogated Mn-induced GOLIM4 degradation in 3q-amplified cells, and ectopic coexpression of GOLIM4 and ATP2C1 sensitized a 3q-diploid lung cancer cell line (H23) to Mn treatment." (PMID 38662435, 2024). "While Mn induced GOLIM4 degradation irrespective of 3q amplification status, GOLIM4 degradation occurred more rapidly in 3q-amplified than 3q-diploid lung cancer cells." (PMID 38662435, 2024). "In reconstitution studies carried out on GOLIM4-deficient cells, a short form of GOLIM4 that lacked the alternatively spliced exon (GOLIM4-ΔE7) did not bind to ATP2C1 or rescue secretory, tumorigenic, or metastatic activities of GOLIM4-deficient lung cancer cells." (PMID 38662435, 2024). "Mn decreased intratumoral GOLIM4 levels irrespective of 3q amplification status but exerted greater proapoptotic and antitumor activity in 3q-amplified than 3q-diploid models, including tumors generated by lung cancer cell lines or lung or pancreatic cancer patient–derived xenografts (PDXs)." (PMID 38662435, 2024).
and-neck cancer (2 papers, 2021 to 2025). "The GOLIM4/GPP130 gene enhances cell proliferation via the modulation of key regulators of the cell cycle in head-and-neck cancer cells." (PMID 40649939, 2025).
Parkinson’s (2 papers, 2018 to 2023). "The identification of manganese-sensitive proteins like GOLIM4 as cargo for both AP-5 and retromer provides a potential clue, because failure to deal with toxic levels of Mn2+ has been shown to cause neurodegeneration and parkinsonism." (PMID 29381698, 2018).
cancer (11 papers, 2015 to 2025). A tumor composed of atypical neoplastic, often pleomorphic cells that invade other tissues. "This led us to analyze the cBioPortal for Cancer Genomics, revealing that the GPP130/GOLIM4 gene is amplified in many cancers, including lung, ovarian, and cervical." (PMID 40649939, 2025). "Multiple GOLIM4-dependent secreted proteins maintained the viability, motility, invasion, and colony-forming activities of cancer cells, and Mn treatment inhibited the secretion of key effectors." (PMID 38662435, 2024). "In this study, we investigated the role of GOLIM4 in 3q-amplified malignancies and found that GOLIM4 recruited client proteins that coordinated secretory vesicle biogenesis and activated a heightened secretory state." (PMID 38662435, 2024). "Our study demonstrates that Mn can target cancer cells by degrading the oncoprotein GOLIM4, suggesting its potential as a targeted therapy." (PMID 38662435, 2024). "Lastly, some genes (HMGN5, IRS1, PHGDH, MXRA5, GOLIM4, and SFRP2) are associated with the development of multiple cancer types." (PMID 33924951, 2021). "Determining the effects of the GOLIM4-driven secretome on stromal cells, and particularly on the immune system, will strengthen the case for preclinical evaluation of Mn2+ therapy for the treatment of 3q-amplified cancers." (PMID 40047887, 2024). "In this issue of the JCI, Tan and colleagues describe functional cooperativity between the Golgi-resident proteins Golgi integral membrane protein 4 (GOLIM4) and ATPase secretory pathway Ca2+ transporting 1 (ATP2C1) in the coordination of a secretory program in 3q-amplified cancers." (PMID 40047887, 2024). "GOLIM4 and RNF139 in this PM were found as potential cancer drivers in various types of cancers." (PMID 26317392, 2015).
tumor (9 papers, 2016 to 2025). "Here we profiled alternative splicing events in NPC tumor samples using transcriptome analysis, which revealed an alternative splicing variant of GOLIM4 to be associated with the survival of patients with NPC." (PMID 34180133, 2021). "We identified a region of chromosome 3q that is amplified in diverse tumor types and encodes multiple regulators of secretory vesicle biogenesis, including the Golgi scaffold Golgi integral membrane protein 4 (GOLIM4) and its client protein ATPase secretory pathway Ca2+ transporting 1 (ATP2C1)." (PMID 38662435, 2024). "Targeting these tumors with manganese (Mn2+) promoted GOLIM4 degradation and imposed a secretory blockade that impaired tumor progression and stromal cell recruitment in mice." (PMID 40047887, 2024). "Following CRISPR/Cas-9-mediated GOLIM4 depletion, 344SQ cells exhibited reduced proliferative and migratory activity in culture and decreased tumor growth and metastatic activity in mice." (PMID 38662435, 2024). "Therefore, we postulated that GOLIM4 activates protumorigenic secretory processes and tested this hypothesis by carrying out immunohistochemical studies on GOLIM4-deficient and -replete tumors, which showed that GOLIM4 deficiency reduced endothelial cell numbers in tumor stroma." (PMID 38662435, 2024). "Systemic manganese (Mn) delivery to mice bearing chromosome 3q–amplified malignancies degrades intratumoral GOLIM4, inhibits secretion, and induces tumor regression." (PMID 39225096, 2024). "Fifth, a GOLIM4 mutant that cannot bind Mn did not rescue the antitumor effects of Mn in GOLIM4-deficient tumor cells, linking GOLIM4 to Mn-induced blockade of a protumorigenic secretory process." (PMID 38662435, 2024). "Thus, increasing Mn2+ levels abrogates GOLIM4-dependent secretory programs and reduces tumor progression." (PMID 40047887, 2024). "Thus, GOLIM4-dependent secretion activated an APP-dependent autocrine loop that drove tumor progression." (PMID 38662435, 2024). "We show that Mn treatment inhibited the progression of multiple types of 3q-amplified malignancies by degrading GOLIM4, resulting in a secretory blockade that interrupted prosurvival autocrine loops and attenuated prometastatic processes in the tumor microenvironment." (PMID 38662435, 2024). "Fourth, a GOLIM4 splice variant that cannot bind ATP2C1 did not enhance secretion or promote tumor growth, linking ATP2C1-binding activity to a protumorigenic secretory process activated by GOLIM4." (PMID 38662435, 2024). "Although the Golgi apparatus may be involved in tumor biological processes, the function of GOLIM4 during tumorigenesis remains unclear." (PMID 37760246, 2023). "Pharmacologic strategies to degrade GOLIM4 or inhibit GRASP55/client interactions induce secretory blockade and tumor regression." (PMID 39225096, 2024). "A number of interferon-stimulated genes (ISGs) were found to be highly induced in tumor compared to non-tumor samples, such as GBP1, CAMP, PTGS2, GOLIM4, IFIT3, MX1, LTF, and CYBB." (PMID 34400640, 2021). "Expression of GOLIM4, a Golgi integral membrane protein, was lower in tumour cells compared with HCO (P<0.001), and upregulated in 143B100, 143BNSC and 143BGBM tumours at early progression (P<0.001) and downregulated at late progression (P<0.001)." (PMID 27551510, 2016). "Furthermore, in GOLIM4-deficient cells reconstituted with a GOLIM4 mutant that does not bind to Mn, Mn did not degrade GOLIM4, inhibit secretion, decrease tumor cell viability or migration, or suppress tumor growth or metastasis." (PMID 38662435, 2024). "The amplification of genes such as COL5A1, IDO1, and GOLIM4 were in accordance with their higher expression in tumor samples, whereas no significant change of protein or phosphorylation levels was observed for genes with genomic amplification, such as CD4, CD7, LIME1, UNC93B1, C1S, C1R, or C8G." (PMID 34400640, 2021).
infection (2 papers, 2015 to 2020). The state of being infected such as from the introduction of a foreign agent such as serum, vaccine, antigenic substance or organism. "As the GOLIM4 provides the infectious protein Shiga toxin with a means of escaping the degradation system of the late endosome, downregulation of the GOLIM4 may result in the accumulation of Shiga toxin in the early endosome, which would consequently help inhibit infection." (PMID 33187521, 2020).
GOLIM4 also shares sentences with these, for which no sentence is quoted: cervical cancer (1 paper); Cognitive impairment (1); epilepsy (1); leukemia (1); nasopharyngeal carcinoma (1); ovarian carcinoma (1); pancreatic cancer (1).